PDS5B (PDS5 cohesin associated factor B)
Diseases named in the same sentence as PDS5B in open-access papers (continued):
Sharing a sentence is not in itself a finding about the gene and the disease.
tumor (99 papers, 2007 to 2025). "Because anthracycline is a DNA-intercalating agent and causes DNA damage, the DNA-repair mechanism is probably weakened in tumor cells with low expression of PDS5B." (PMID 34070827, 2021). "PDS5B has been suggested as a tumor suppressor because its expression is reduced or lost in many cancer types." (PMID 34070827, 2021). "Consistently, ectopic overexpression of PDS5B reversed miR-223-mediated tumor progression in PC cells." (PMID 30776580, 2019). "Taken together, these data indicate that the presence of tumor-derived STAG2 mutations results in a decrease in levels of cohesin and a reduction in ability of WAPL, PDS5A, and PDS5B to interact with cohesin." (PMID 26871722, 2016). "We found that PDS5B overexpression reduced tumor growth compared with the control group." (PMID 34226509, 2021). "PDS5B has been reported to involve in tumorigenesis and tumor progression." (PMID 34226509, 2021). "The tumor weights and volumes were less in the PDS5B-overexpressing group." (PMID 34226509, 2021). "We also observed that PDS5B overexpression retarded tumor growth in nude mice." (PMID 34226509, 2021). "We found that PDS5B overexpression inhibited cell growth and invasion, whereas downregulation of PDS5B promoted cell motility, suggesting that PDS5B could be a tumor suppressor in PC." (PMID 30776580, 2019). "Furthermore, the analysis indicated that the CHD1 is an oncogene and that PDS5B is a tumor suppressor." (PMID 31222142, 2019). "Altogether, these results coherently support the notion that PDS5B could play a tumor-suppressive role in PC cells." (PMID 30776580, 2019). "Furthermore, heterozygosity of genomic region containing Pds5b has been detected in a number of tumors and thus Pds5b has been nominated as a potential tumor suppressor gene." (PMID 26334628, 2015). "Moreover, PDS5B exhibits tumor-suppressive function in PC cells." (PMID 30776580, 2019). "For instance, for CRUK0048, a LUAD tumour with 11 clones, ALPACA inferred LOH affecting 13q12.12–13q14.3 (encompassing BRCA2, PDS5B and RB1) to occur in primary tumour clone 2, before seeding a recurrence metastasis lesion." (PMID 40804524, 2025). "When a tumor lacks PDS5B, depletion of PDS5A is expected to inhibit the tumor’s growth, and vice versa." (PMID 34070827, 2021). "PDS5B was detected to be expressed in 39 tumor tissues, and 193 patients displayed no detectable expression of PDS5B." (PMID 34226509, 2021). "Furthermore, the expression of PDS5B and LATS1 was determined in mouse tumor tissues by western blotting." (PMID 34226509, 2021). "Interestingly, one group reported that PD-L1 competes with WAPL to bind to PDS5B and performs tumor progression independent of its role in the immune checkpoint." (PMID 34226509, 2021).
cancer (98 papers, 2014 to 2026). A tumor composed of atypical neoplastic, often pleomorphic cells that invade other tissues. "It is also of interest that the human BRCA2 gene neighbors PDS5B, with some cancer-associated mutations likely altering both genes." (PMID 29447171, 2018). "Future studies should investigate whether mutations in ATRX disrupt its interaction with Pds5B and how such changes might contribute to chromosomal instability in cancer." (PMID 40437074, 2025). "PDS5B coordinates the differentiation of stem cells, and knockdown of PDS5B causes the failure of differentiation and results in immature proliferative cells that are similar to the cancer-initiation cells." (PMID 34070827, 2021). "PDS5B, also known as APRIN and AS3, is a candidate tumour suppressor mutated or downregulated in a variety of cancer types." (PMID 40437196, 2025). "A mechanism whereby PDS5B depletion promotes proliferation of cancer cells is possible through the IL-6/STAT3/cyclin D axis." (PMID 34070827, 2021). "Depletion of PDS5B in cancer cells induces secretion of interleukin-6 (IL-6), which binds to its receptor and in turn activates intracellular STAT3." (PMID 34070827, 2021). "This information suggests targeting IL-6/STAT3/cyclin D axis in cancers with low PDS5B might provide a novel therapeutic approach." (PMID 34070827, 2021). "According to a well‐defined dataset of cancer‐associated genes (CAG) to nominate functionally important genes with cis‐regulatory effects, 551 genes were identified in our cohort, including PDS5B, which showed cis effects at multiple omics levels in both T and LM." (PMID 41195591, 2026). "The low PDS5B expression may be regulated by epigenetic modifications, especially methylation, of CpG island of PDS5B promoter, and PDS5B reduction might promote cancer cell proliferation through the IL-6/STAT3/cyclin D axis." (PMID 35509102, 2022). "As PDS5B might be a useful target for fighting cancer, it is pivotal to discover the compounds to modulate the expression of PDS5B and to obtain a better treatment outcome for cancer patients." (PMID 34226509, 2021). "Remarkably, we found that deletion of the cohesin regulator PDS5B is a common event in PCA, as well as in other types of cancer." (PMID 31222142, 2019). "Moreover, silencing of PDS5B expression promotes cell proliferation via induction of IL-6 secretion and activation of STAT3, and promotion of cyclin D1 expression in human cancer." (PMID 34226509, 2021).
PDS5B also shares sentences with these, for which no sentence is quoted: bladder cancer (27 papers); hepatocellular carcinoma (25); glioma (17); colon cancer (13); non-small cell lung carcinoma (11); esophageal cancer (6); liver cancer (5); lymph node metastasis (5); atherosclerosis (4); cervical squamous cell carcinoma (3); osteosarcoma (3); colon adenocarcinoma (2); glioblastoma (2); infection (2); intervertebral disc degeneration (2); leukaemia (2); melanoma (2); nasopharyngeal carcinoma (2); acute lymphoblastic leukemia (1); acute promyelocytic leukemia (1); adenocarcinoma (1); Alzheimer disease (1); anal adenocarcinoma (1); blood neoplasms (1); Brain atrophy (1); cardiovascular disorder (1); chordoma (1); Cirrhosis (1); clear cell renal cell carcinoma (1); esophageal tumors (1).
A further 28 diseases each share a sentence with PDS5B in 1 paper.